RUNX3 (RUNX family transcription factor 3)
Diseases named in the same sentence as RUNX3 in open-access papers (continued):
Sharing a sentence is not in itself a finding about the gene and the disease.
cancer (continued). "In contrast, we detected RUNX3 at low levels in 11 AGCT tissues obtained from the Alberta Cancer Research Biobank, but in none of the six AGCT from Baylor College of Medicine Tissue Repository." (PMID 31311113, 2019). "The CpG methylations of RUNX3 and TGF-β were increased in the metastatic renal cancer model, while the global methylations of RUNX3 and TGF-β were decreased, consistent with the human cancer tissue results." (PMID 29651226, 2018). "More than a decade ago RUNX3 was catalogued as a major TSG in GC and in other cancers." (PMID 27566570, 2016). "Expression of three target genes (H2AFX, RUNX3 and MTHFD1L) of miR-133a and one target gene (FYB) of miR-206 was upregulated while expression of these two miRNAs (miR-133a and miR-206) were significantly downregulated in cancer tissues." (PMID 27597234, 2016). "In the case of RUNX3, we observed its methylation in only one cell line and thus did not analyze its methylation in primary carcinoma patients." (PMID 25487617, 2015). "The success of these therapies may in part be due to removal of aberrant hypermethylation at CpG islands within promoter regions of key cancer genes including KLF4, RUNX3, and RSU1 identified as hypermethylated in our data." (PMID 25294808, 2014). "By immunohistochemistry, RUNX3 expression was observed in normal colon mucosa, while cancer cells did not express RUNX3." (PMID 19521519, 2009). "AIM2 was selected because it was previously thought to be a TSG that is frequently hypermethylated in cancer and because, unlike RUNX3, it becomes unmethylated specifically in the myeloid lineage." (PMID 18820729, 2008). "Methylation of RUNX3 was present in 63.6% (14 in 22 cases) of cancers and 27.2% (six in 22 cases) of noncancerous adjacent mucosa, which correlated with RUNX3 expression." (PMID 15685235, 2005). "However, CRLs are also present in SCF complex E3 ligases, which are recruited by RUNX3 to degrade oncoproteins GLI1, and likely MYCN, so potential cancer treatments may require a more personalized approach." (PMID 36899853, 2023). "However, the mechanism of action through which EZH2 targets and regulates RUNX3 expression and the resulting variations in various behaviors presented in cancer cell life activities have not been elucidated." (PMID 38048186, 2023). "Therefore, even if RUNX3 expression is normal, the expected cancer-suppressive effect of endogenous RUNX3 is not evident in the presence of deletions or mutations in the target genes or co-activator of RUNX3." (PMID 37438719, 2023). "However, the precise mechanism of epigenetic-mediated silencing of TSG RUNX3, which results in cancer invasion and metastasis, has not yet been explored." (PMID 35898303, 2022). "Indeed, Runx3 expression corelates with the intra-tumoral residency of CD8+ TRM cells within human tumors, thus, being a strong indicator of favorable outcomes of various cancers." (PMID 36231078, 2022). "We are not the first to study RUNX3 methylation as a cancer biomarker." (PMID 26682246, 2015). "Similarly, TSP-1 is a potent inhibitor of angiogenesis and tumorigenesis; still, the role of Runx3 in transcriptional regulation of TSP-1 in cancer cells is not studied in detail." (PMID 23846726, 2013).
cancer (continued). "To investigate further the role of promoter DNA methylation of genes aberrantly hypermethylated in cancer in hESCs, we compared the DNA methylation and expression status of four of the genes identified in the methylation arrays (MGMT and SLC5A8 from Class B-I, and PYCARD and RUNX3 from Class B-II)." (PMID 18820729, 2008). "Finally, methylation of CRABP1, MLH1, NR3C1, RUNX3, and SCGB3A1 were identifiers of MSI carcinomas." (PMID 19117505, 2008). "Furthermore, the extent of methylation was significantly greater in EAC compared to BE for six genes (CDKN2A, ID4, RBP1, RUNX3, SFRP1, and TMEFF2), suggesting that methylation of these genes occurs early in the progression of BE, with increased methylation as the disease advances toward cancer." (PMID 40149421, 2025). "The RUNX3 knockout pig model exhibited its role in cancer mechanisms by demonstrating that the absence of the tumor suppressor gene RUNX3 could lead to early gastric tumorigenesis, aligning with its known function in suppressing cancerous developments in human gastric cells." (PMID 39595585, 2024). "Other transcription factors (TP73, ERBB4, TBX5 and RUNX3) detected variations across cell lines, with TP73 being notably upregulated in four cancer lines except for SqCC/Y1." (PMID 35000271, 2022). "Since RUNX3 is reportedly hypermethylated in various cancer types, including lung cancer, we speculate that Wnt inhibitors, such as vantictumab and LGK974, which are currently in clinical trials for other cancer types, may be useful in the treatment of pan-negative cases." (PMID 38433247, 2024).
infection (25 papers, 2014 to 2025). The state of being infected such as from the introduction of a foreign agent such as serum, vaccine, antigenic substance or organism. "The roles of RUNX3 further extend into ILC1 and ILC3 homeostasis, as RUNX3 deficiency in ILC1s and ILC3s results in uncontrollable infection with C. Rodentim." (PMID 36231078, 2022). "Having demonstrated altered TE/MP subset distribution in MAZR- and/or Runx3-deficient CTLs, we next characterized memory T cells in the mutant mice thirty days after infection." (PMID 33815354, 2021). "In this report, using S. typhimurium and L. monocytogenes, we found that the levels of group 1 ILCs and NCR+ ILC3s were increased upon infection and that these increases were associated with Runt-related transcription factor 3 (Runx3) expression." (PMID 30258450, 2018). "All of the Runx3-restored mice began to die at 20 weeks after tamoxifen treatment (26 weeks after Ad-Cre infection)." (PMID 37887282, 2023). "In conclusion, upon infection with S. typhimurium, Nkp46+ILC3s upregulated Runx3 expression, which promotes the IL-12/STAT4/IFN-γ signaling pathway, and which would in turn limit intracellular bacterial infection." (PMID 34659248, 2021). "Runx3 fl/fl PLZF-cre mice were much more sensitive to infection with the intracellular bacterial pathogens S. typhimurium and L. monocytogenes partially due to abnormal Group 1 ILC and NCR+ILC3 function." (PMID 30258450, 2018). "Quantitative real-time PCR revealed that Runx3 mRNA was induced by H1N1 12 h post-infection and reached a maximal level at 20 h in BEAS-2B cells." (PMID 26643317, 2015). "Analysis of CD4+ T-cell populations shows that upon activation of naïve CD4+ T-cells (a population relatively refractory to infection) the expression levels of RUNX1, RUNX3 and CBF-β drop (correlating with greater susceptibility to infection)." (PMID 24651404, 2014). "T-bet, RUNX3, and EOMES are attenuated in CD8 + CD38 + T cells from SLE patients, resulting in a decrease in CD8 T cell-mediated cytotoxicity and an increase in susceptibility to infection." (PMID 38650001, 2024). "Notably, the intracellular expression of Runx1 and Runx3 remained unchanged despite SbRLD or SbSLD infection or SAG treatment (right two panels)." (PMID 33370418, 2020). "Thus, selective manipulation of Nr4a1 expression may serve as a potential strategy to boost CD8 T cell response against infection and during vaccination through its manipulation of Runx3." (PMID 25762306, 2015). "We also collected faces at day 5 post-infection and higher S. typhimurium colony counts were obtained from the faces of NCG mice injected with ILC1s sorted from Runx3 cKO mice." (PMID 30258450, 2018). "After infection, the expression of IL12Rβ2 was decreased in ILC1s from the liver, and in ILC1s and NCR+ILC3s from the small intestine in Runx3 cKO mice." (PMID 30258450, 2018). "Ten days after infection, the NCG mice injected with ILC1 cells sorted from Runx3 cKO mice exhibited significantly shorter colon length." (PMID 30258450, 2018). "TUNEL staining (green color) revealed that infection of BEAS-2B cells with H1N1 induced cell apoptosis, and the apoptotic rate was markedly augmented (2.6-fold) by Runx3 overexpression." (PMID 26643317, 2015). "Notably, 12 of these TFs exhibited distinct phosphorylation patterns upon infection, including MED14, SIN3A, BCL6, cJUN, NFATC1, STAT3, RUNX3, GTF2F1, MED1, JUNB, TLE3, and FOSL2." (PMID 40368139, 2025). "TH1- and TH2-related transcripts included Nfatc1, Cd4, Runx3, and Gata3, suggesting that TH1 cells may be a significant contributor to interferon-gamma (IFNγ) production during infection in the adipose tissue." (PMID 37923768, 2023). "In addition, a small group of transcription factors was predicted to be inhibited only upon infection with amastigotes (SOX6, RUNX3, and STAT1) or promastigotes (TRIM24, SIRT1, and FOXP3)." (PMID 35430587, 2022).
infection (continued). "As a control for RUNX3, CBFβ and IRF4 depletion experiments, EBNA2 ChIPs were performed in a similar manner, on the same batch of chromatin, after their infection with each shRNA-expressing lentivirus to show that the trend of reduced EBNA3 enrichment after knock-down was specific." (PMID 27903901, 2017). "RUNX3 protein levels were upregulated 2.5-fold on infection of EBV negative BL31 cells with wild-type EBV, with cells infected with revertant viruses expressing similar levels to wild type infected cells, as expected." (PMID 26883634, 2016). "However, neither SAG treatment nor LD infection had any effect on Runx1 and Runx3 expression in BMDCs (right two panels)." (PMID 33370418, 2020).
adenocarcinoma (13 papers, 2008 to 2025). A common cancer characterized by the presence of malignant glandular cells. "Their results showed two hypomethylated genes (CDKN2A and MGMT) and three hypermethylated genes (CDH13, RUNX3, APC) in adenocarcinomas compared with SCC, with the higher sensitivity and specificity values of CDH13 and APC." (PMID 32604993, 2020).
lung (6 papers, 2015 to 2023). "Runx3 is inactivated in nearly all the human and mouse lung ADs and, to date, Runx3 is the only gene whose inactivation has been reported to induce lung AD." (PMID 36899846, 2023). "We previously showed that Runx3 is downregulated in most of K-Ras-activated human and mouse lung ADC cells." (PMID 31015486, 2019). "Further, we investigated the interactions between RUNX3 and ZEB1 and the involvement of the interactions between RUNX3 and ZEB1 in chronic lung injury induced by long-term exposure to MA." (PMID 36479199, 2022).
bacterial infection (3 papers, 2018 to 2022). "To address the function of Runx3 function in group 1 ILC and NCR+ILC3 against intracellular bacterial infection, we generated Runx3-deficient mice by crossing mice with loxP-flanked Runx3 alleles (Runx3fl/fl) with PLZF-cre mice." (PMID 30258450, 2018). "After conditional knockout of Runx3, we found that mice were more sensitive to intracellular bacterial infection, namely, S. typhimurium and L. monocytogenes." (PMID 30258450, 2018). "Subsequently, the overexpression of Runx3 can then promote IL12-STAT4-IFNγ signaling to limit intracellular bacterial infection." (PMID 30258450, 2018). "Therefore, our data reveal a previously unknown protective function of Runx3 in orchestrating innate immunity against intercellular bacterial infection." (PMID 30258450, 2018). "The expressions of Zbtb7b and RUNX3 restrict each other, affect the response of CD4+ T cells, and impair intestinal inflammatory immunity and the probability of exogenous bacterial infection." (PMID 35761286, 2022). "To investigate the role of Runx3 in mediating group 1 ILCs and NCR+ILC3s against intracellular bacterial infection, we generated PLZF-cre Runx3 cKO mice (PLZF-cre Runx3 fl/fl are hereafter referred to as Runx3 cKO mice)." (PMID 30258450, 2018). "To further address the function of Runx3 in intestinal group 1 ILCs and NCR+ILC3s during intracellular bacterial infection, we used the S. Typhimurium infection model." (PMID 30258450, 2018). "Although a considerable number of studies investigated the role of Runx3 in T-cell lineage commitment and function, as well as in ILC development, little is known about its function in ILCs against intracellular bacterial infection." (PMID 30258450, 2018). "Therefore, we demonstrate that Runx3 influences group 1 ILC- and NCR+ILC3-mediated immune protection against intracellular bacterial infections of both the gut and liver." (PMID 30258450, 2018).
benign neoplasm (2 papers, 2017 to 2019). A neoplasm which is characterized by the absence of morphologic features associated with malignancy (severe cytologic atypia, tumor cell necrosis, and high mitotic rate). "Similarly, the hypermethylation rate of RUNX3 in IDC was also significantly higher than in NB or benign tumor." (PMID 27825140, 2017). "In addition, RUNX3 methylation was significantly increased in IDC than in benign tumor, OR was 55.65 with 95% CI 9.99-310.15, z = 4.59, p < 0.00001, I2 = 0%, p = 0.73." (PMID 27825140, 2017).
haematological disorders (2 papers, 2022 to 2024). "Additionally, we found actors involved in the activation of transcription factors such as NF-κB and RUNX3, which have both been implicated in the development of hematological malignancies." (PMID 38918490, 2024). "Taken together, this study demonstrates that the downregulation of RUNX3 observed in normal human erythropoiesis is important in promoting the terminal stages of erythroid development and may further our understanding of the role of this transcription factor in haematological disorders." (PMID 35075235, 2022).
GI tumor (1 paper, 2008). "In many CRCs, RUNX3 expression is low, consistent with a role in GI tumor suppression." (PMID 18551179, 2008).
renal diseases (1 paper, 2022). "A comparison of the area under the curve (AUC) profiles on multiple receiver operating characteristic curves of the DEGs in DKD and other renal diseases revealed that REG1A and RUNX3 had the highest specificity for DKD diagnosis." (PMID 35937821, 2022).
skeletal diseases (1 paper, 2023). "In mammals, three RUNX members, namely RUNX1, RUNX2, and RUNX3, play distinct and redundant roles, although RUNX2 is a dominant factor in skeletal development and several skeletal diseases." (PMID 37436583, 2023).
RUNX3 also shares sentences with these, for which no sentence is quoted: Crohn disease (4 papers); myeloma (3); Barrett esophagus (2); basal cell carcinoma (2); bronchopulmonary dysplasia (2); chordoma (2); colon adenocarcinoma (2); colorectal adenocarcinoma (2); ductal carcinoma in situ (2); hepatoblastoma (2); immune diseases (2); infectious (2); influenza infection (2); lung squamous cell carcinoma (2); Peptic ulcer (2); retinoblastoma (2); rheumatoid arthritis (2); Wilms tumor (2); acute graft versus host disease (1); acute leukemia (1); acute pancreatitis (1); acute promyelocytic leukemia (1); allergic disease (1); Alzheimer disease (1); anaemia (1); ankylosis (1); atopic asthma (1); autism spectrum disorder (1); B cell lymphoma (1); Behçet’s disease (1).
A further 54 diseases each share a sentence with RUNX3 in 1 paper.